HSPA1A (heat shock protein family A (Hsp70) member 1A)
Diseases named in the same sentence as HSPA1A in open-access papers (continued):
Sharing a sentence is not in itself a finding about the gene and the disease.
depression (4 papers, 2014 to 2026). "The analysis of mRNA expression in the prefrontal cortex of suicide victims with major depressive disorder revealed a differential profile with 27 downregulated mRNAs, including HSPA1A, HSPA1B, DNAJB1, NR4A1, and GADD45B, which are involved in proteostasis, transcriptional regulation, and apoptosis." (PMID 41977312, 2026). "Moreover, it has also been shown that HSPA1A is also a gene that mediates the interaction between AD and depression." (PMID 38516314, 2024).
glioma (4 papers, 2019 to 2025). A benign or malignant brain and spinal cord tumor that arises from glial cells (astrocytes, oligodendrocytes, ependymal cells). "HSPA1A codes for a 70 kDa heat shock protein (Hsp70), and high HSPA1A expression activity has been associated with increased cancer cell proliferation, including in glioma." (PMID 38351133, 2024). "Through comprehensive bioinformatic analysis and in vitro function assays, we found that NONHSAT079852.2 acts as a sponge for has-mir-10401-3p to increase HSPA1A expression and thereby promotes the proliferation, migration, and invasion of glioma cells." (PMID 34307121, 2021). "The knockdown of NONHSAT079852.2 successfully induced tumor cell apoptosis, inhibited the proliferation, migration, invasion and the expression level of HSPA1A in glioma cells." (PMID 34307121, 2021). "In gliomas, heat shock protein 70 (Hsp70, HSPA1A) is overexpressed in the cytoplasm." (PMID 40777122, 2025). "Moreover, the knocking down of NONHSAT079852.2 inhibited the proliferation of glioma cells by downregulating HSPA1A expression." (PMID 34307121, 2021).
ischemia (4 papers, 2012 to 2025). A hypoperfusion of the BLOOD through an organ or tissue caused by a PATHOLOGIC CONSTRICTION or obstruction of its BLOOD VESSELS, or an absence of BLOOD CIRCULATION. "HSPA1A was shown to inhibit the production of proinflammatory factors (TNF-α and IL-6) and inhibit the activity of matrix metalloprotein kinases (MMPs) and iNOS in both in vitro and in vivo models of ischemia." (PMID 39924492, 2025).
Parkinson disease (4 papers, 2011 to 2025). A progressive degenerative disorder of the central nervous system characterized by loss of dopamine producing neurons in the substantia nigra and the presence of Lewy bodies in the substantia nigra and locus coeruleus. "The misfolding and the aggregation of proteins are common characteristics of several neurodegenerative diseases including AD and Parkinson's disease, therefore it is very likely that HSPA1A may also characterize AD." (PMID 21726470, 2011).
prion disease (4 papers, 2012 to 2023). A transmissible disease that is caused by a protein that is able to induce abnormal folding of normal cellular proteins, leading to characteristic spongiform brain changes, which are associated with neuronal loss without an inflammatory response. "According to the GeneSpring analysis results, HSPA1A was up-regulated and participated in spliceosome, antigen processing and presentation, endocytosis, MAPK signaling pathway, and prion diseases using the KEGG pathway and in T-cell regulation in heat pattern RA patients." (PMID 22536280, 2012).
asthma (3 papers, 2022 to 2024). "The expression of HSPA1A, PIK3CG and PIK3R6 was associated with moderate asthma, while MAPK13 and MMP9 were associated with severe asthma." (PMID 39088141, 2024). "Among the genes involved in these important signaling pathways, HSPA1A, PIK3CG and PIK3R6 seemed to be associated with moderate asthma, while MAPK13 and MMP9 appeared to be associated with severe asthma." (PMID 39088141, 2024). "We also used the fitted logistic regression model to predict the probability that, in a given individual, asthma and asthma evolution signs occurred, based on the concentration of FeNO and the HSPA1A/B expression." (PMID 35982171, 2022). "In other words, the odds ratio of asthma symptoms increased by a factor 7.7 for a unit decrease in ∆Ct of HSPA1A/B." (PMID 35982171, 2022). "The increase in HSPA1A levels was found to be related to the severity of asthma." (PMID 39088141, 2024). "Overall, this study discovered a total of five genes, including HSPA1A, PIK3CG, PIK3R6, MAPK 13 and MMP9, as potential biomarkers of moderate or severe asthma." (PMID 39088141, 2024). "The expression of HSPA1A, PIK3CG and PIK3R6 in the same 10 and 4 pathways was then verified, while the expression of MAPK13 and MMP9 related to severe asthma was also confirmed." (PMID 39088141, 2024). "As this lack of correlation with SPT sensitization, and thus to the duration of inflammation, supports the hypothesis of a direct link between HSPA1A/B expression and lower airways inflammatory signals, these data would suggest a potential usefulness of HSP70 also in asthma of non-allergic origin." (PMID 35982171, 2022).
Autoimmunity (3 papers, 2020 to 2023). The occurrence of an immune reaction against the organism's own cells or tissues. "This promiscuity may allow HSPs, including HSPA1A and HSPB1, flexibility in responding to pathogens and other sterile threats, but also increases the potential for cell and tissue damage or autoimmunity if for any reason the anti‐inflammatory response is inhibited." (PMID 37583307, 2023).
breast tumors (3 papers, 2021 to 2022). "We therefore next examined the co-expression correlation between HSPs and co-chaperones including HSP90 family (HSP90AA1, HSP90AB1), HSP70 family (HSPA1A, HSPA1B, HSPA8) and BAG family (BAG1, BAG2, BAG3) among 960 breast tumor samples registered in the Cancer Genome Atlas (TCGA)." (PMID 36114410, 2022).
heart failure (3 papers, 2016 to 2021). Inability of the heart to pump blood at an adequate rate to meet tissue metabolic requirements. "Hspa1a upregulation is linked with HF diet associated oxidative stress in patients with metabolic syndrome, correlates with HbA1c levels in maternal diabetes, and is proposed as an independent prognostic marker in patients with heart failure and cardiac arrest." (PMID 28425976, 2017). "This suggests that Hspa1a may be a relevant marker linking maternal diabetes and offspring heart failure." (PMID 34803741, 2021). "Hspa1a has been proposed as an independent prognostic marker of heart failure." (PMID 34803741, 2021).
liver cancer (3 papers, 2009 to 2024). An epithelial or non-epithelial malignant neoplasm that arises from the liver. "Interestingly, the upregulation of HSPA1A expression in liver cancer samples indicates its potential involvement in tumor progression." (PMID 37993485, 2023). "Heat shock 70KDa protein 1A (HSPA1A) is up regulated in brain, lung, and liver cancer." (PMID 19347046, 2009). "The expression of HSPA1A and IKBKE was significantly elevated in liver cancer tissues, consistent with our previous findings." (PMID 39000042, 2024).
mild cognitive impairment (3 papers, 2022 to 2025). "As for ECs, we also saw upregulation of certain heat shock protein genes, such as HSPA1A, which in the cerebrospinal fluid have been associated previously with cognitive impairment in AD." (PMID 39807599, 2025). "A proteomics analysis of extracellular vesicles isolated from cerebrospinal fluid in AD also revealed elevated expression of HSPA1A compared to the mild cognitive impairment and control groups." (PMID 37735671, 2023).
multiple sclerosis (3 papers, 2020 to 2024). A progressive autoimmune disorder affecting the central nervous system resulting in demyelination. "Cluster 3 highly expressed heat shock protein HSPA1A, an immediate early gene reportedly involved in antigen processing, response to stress and injury and exhibiting decreased gene expression in multiple sclerosis patients." (PMID 35388616, 2022).
prostate carcinoma (3 papers, 2011 to 2024). A carcinoma that arises from epithelial cells of the prostate gland. "Consistent with our findings in prostate cancer patients, radiation exposure resulted in a significant increase in serum HSPA1A/B concentrations in both human xenografts and syngeneic tumor-bearing mice." (PMID 24213112, 2011). "Our group further assessed the impact of common treatments for prostate cancer on serum HSPA1A/B levels and to characterize its mechanism of release and biological significance using Mouse orthotopic xenograft of human prostate cancer." (PMID 24213112, 2011). "IPA® projected the association of several proteins’ downregulation, including heat shock protein families α and β (HSPA1A/HSPA1B) and peptidylprolyl isomerase A (PPIA), with prostate cancer apoptosis." (PMID 39598420, 2024). "Immunohistochemical analysis of HSPA1A/B expression revealed similar expression of HSPB1 in early prostate cancers compared with non-neoplastic controls, but diminished expression was noted in morphologically advanced cancers." (PMID 24213112, 2011).
pulmonary fibrosis (3 papers, 2022 to 2025). Chronic progressive interstitial lung disorder characterized by the replacement of the lung tissue by connective tissue, leading to progressive dyspnea, respiratory failure, or right heart failure. "In addition, HSPA1A has been linked to a lower incidence of pulmonary fibrosis." (PMID 37180137, 2023). "Next, we examined the gene and protein expression of Rfx2, one of three common upregulated genes among the three combinations of nintedanib- and vehicle-treated mice based on progression of pulmonary fibrosis (Rfx2, Hspa1a, and Hspa1b), and Bmpr2." (PMID 35714115, 2022). "In the present study, fewer upregulated genes than downregulated genes were detected, and among the 3 combinations of nintedanib- and vehicle-treated mice based on the progression of pulmonary fibrosis, only three common upregulated genes were identified (Rfx2, Hspa1a, and Hspa1b)." (PMID 35714115, 2022).
Sepsis (3 papers, 2015 to 2020). Sepsis is defined as life-threatening organ dysfunction caused by a dysregulated host response to infection. "The transient overexpression of an active form of HSPA1A/B by way of an adenovirus in the lungs of ARDS rats can specifically arrest sepsis-induced apoptosis in alveolar type-1 cells, thereby greatly increasing animal survival." (PMID 25847399, 2015). "Using a rat model for ARDS, it has been shown that an adenoviral vector expressing the stress-inducible form of HSP70, HSPA1A, can effectively protect against sepsis-induced ARDS by limiting neutrophil accumulation in the lungs and causing the inactivation of IκB complexes." (PMID 33043037, 2020). "Results showed that TNF, HSPA1A, HSPA1B, TREM1, SOD2 and MIF genes related to sepsis correspond to m6A-cis-eQTLs." (PMID 32174955, 2020).
basal cell carcinoma (2 papers, 2022 to 2023). A carcinoma involving the basal cells. "In line with this idea, prior study showed that Hspa1a gene was upregulated after anti-PD1 treatment in responder CD8 T cells in basal cell carcinoma patients." (PMID 36330507, 2022).
breast invasive carcinoma (2 papers, 2022 to 2025). "According to the GEPIA2 database, both HSPA1A and HSPA1B are significantly highly expressed in breast invasive carcinoma (BRCA) compared to healthy tissue." (PMID 40426862, 2025).
cardiac hypertrophy (2 papers, 2016 to 2025). "Similarly, published data suggest that during cardiac hypertrophy heat shock proteins Hspa1a and 1b are elevated." (PMID 27548259, 2016).
colitis (2 papers, 2017 to 2023). Inflammation of the colon. "In mice, Hspa1a and Hspa1b double knockout mice were phenotypically normal; however, when treated with dextran sulfate sodium and exposed to oxidative stress, they exhibited colitis." (PMID 28126021, 2017).
colon adenocarcinoma (2 papers, 2021 to 2023). "HSPA1A was associated with poor prognosis of colon adenocarcinoma, liver hepatocellular carcinoma and adrenocortical carcinoma and good prognosis of pheochromocytoma and paraganglioma." (PMID 34712697, 2021). "qRT-PCR validation results verified that HSPA2 was down-regulated in stomach adenocarcinoma and colon adenocarcinoma, HSPA7 and HSPA1A also were down-regulated in colon adenocarcinoma tissues." (PMID 34712697, 2021). "The qRT-PCR validation results in vivo showed that HSPA2 was down-regulated in stomach adenocarcinoma and colon adenocarcinoma; HSPA7 and HSPA1A also were down-regulated in colon adenocarcinoma." (PMID 34712697, 2021).
endothelial dysfunction (2 papers, 2021 to 2022). In vascular diseases, endothelial dysfunction is a systemic pathological state of the endothelium (the inner lining of blood vessels) and can be broadly defined as an imbalance between vasodilating and vasoconstricting substances produced by (or acting on) the endothelium. "Given that phosphorylated HSF1 is responsible for the activation of Hspa1a transcription, our findings suggested that Nar promoted iHSP70 expression via a HSF1-dependent mechanism, by which Nar protected HUVECs against HG-induced endothelial dysfunction." (PMID 35958293, 2022).
Hearing impairment (2 papers, 2017 to 2021). A decreased magnitude of the sensory perception of sound. "Different haplotypes of HSPA1L/HSPA1A/HSPA1B SNP combinations were associated with variable etiologies of hearing impairment." (PMID 33926545, 2021). "In our earlier studies on the associations of HSP70 genetic polymorphisms (HSPA1L/HSPA1A/HSPA1B: rs2075800/rs1043618/rs2763979) with NIHL and sudden sensorineural hearing loss (SSNHL), different haplotypes were associated with diverse risks of these hearing impairments." (PMID 33926545, 2021).
Hypoglycemia (2 papers, 2021). A decreased concentration of glucose in the blood. "Pro-inflammatory interleukin-6 increased at 4-h post-hypoglycemia in controls and T2D (p < 0.05 and p < 0.003, respectively) and correlated with HSPA1A; anti-inflammatory IL-10 decreased 2-h post-hypoglycemia in T2D only." (PMID 34426634, 2021). "The inflammatory response in severe hypoglycemia was restricted to HSPA1A (HSP70), which correlated with IL-6 in the control subjects only." (PMID 34831332, 2021). "In control subjects, HSPB1, SMAD3 and HSPA1A decreased significantly, whilst MAPKAPK5 increased significantly in controls from baseline to hypoglycemia whilst, in T2D, PPP3CA increased and EPHA2 decreased." (PMID 34426634, 2021).
legionellosis (2 papers, 2021 to 2022). Any disease caused by Legionella bacteria. "Interfering a series of human diseases pathways including legionellosis, toxoplasmosis, and measles and some key factors such as MAFF, HSPA1A, HSPA1B, AOC1, and MX2, high doses of moxa smoke influenced the function of rat lungs." (PMID 34961819, 2021).
leishmaniasis (2 papers, 2021 to 2024). Infectious disease that is transmitted through the bite of hematophagous female phlebotomine sand flies. "Through PPI network analysis, hub genes such as Lcn2, Ltf, Mpo, Dnaja1, Hspa1a, Hspa1b and Hsph1 were screened out and might play important roles in the process of undernutrition promoting leishmaniasis." (PMID 38185681, 2024).
lung adenocarcinoma (2 papers, 2021 to 2025). A carcinoma that arises from the lung and is characterized by the presence of malignant glandular epithelial cells. "Furthermore, HSPA1A, whose methylation status is difficult to detect by short reads, may promote the malignant progression of lung adenocarcinoma." (PMID 41187747, 2025).
mastitis (2 papers, 2024 to 2025). Inflammation of breast tissue during lactation or postpartum due to an obstructed duct or infection. "In fact, applied genetic research has shown that expression of the HSPA1A gene can be used to suppress mastitis in Chinese Holsteins." (PMID 38473160, 2024). "It is worth noting that the upregulation of HSPA1A/HSPA1L after CK666 treatment emphasizes a compensatory cytoprotective response that may be an adjuvant treatment strategy for mastitis." (PMID 40305275, 2025).
mesothelioma (2 papers, 2022 to 2025). A usually malignant and aggressive neoplasm of the mesothelium which is often associated with exposure to asbestos. "Additionally, in mesothelioma, the AS factors HSPA1A (heat shock protein family A member 1A) and DDX3Y (DEAD-box helicase Y) regulate the AS of SNX5 (sorting nexin 5), affecting immune evasion and bone metastasis." (PMID 41268214, 2025).
metastatic disease (2 papers, 2020 to 2021). "HSPA1A and HSPA1B were upregulated, while HSPA8 was downregulated in patients with metastatic disease." (PMID 34765552, 2021).
myasthenia gravis (2 papers, 2022). Myasthenia gravis (MG) is a rare, clinically heterogeneous, autoimmune disorder of the neuromuscular junction characterized by fatigable weakness of voluntary muscles. "A study revealed that the ROC result of HSPA1A mRNA in the diagnosis of myasthenia gravis was 0.830." (PMID 36246562, 2022).
oral cancer (2 papers, 2020 to 2023). "This study permitted the proposal of 8 salivary biomarkers for oral cancer in patients previously infected with HPV (RPRD2, PSCA, MCM2, CDKN2A, BAK1, HSPA1A, TANK, MAP2K1)." (PMID 37599356, 2023). "Moreover, sEV derived from oral cancer cells contained a variety of HSPs, including HSP90α (HSP90AA1), HSP90β, TRAP1 (mitochondrial HSP90), HSP105, HSP70 (HSP72/HSPA1A and HSP70B’/HSPA6), GRP78/HSPA5 (ER chaperone), and HSC70." (PMID 32204513, 2020).
osteoporosis (2 papers, 2024 to 2025). A condition of reduced bone mass, with decreased cortical thickness and a decrease in the number and size of the trabeculae of cancellous bone (but normal chemical composition), resulting in increased fracture incidence. "This supports our research findings on Hspa1a inhibiting osteoblast aging and further elucidates the dynamic diversity of m6A modification in regulating osteoporosis." (PMID 38538596, 2024). "However, in parathyroid tissue samples of patients suffering with osteoporosis, HSPA1A-OC parathyroid oxyphilic cells revealed highest cell-cell communication network, highest number of inferred interactions, and highest differential number of interactions and differential interaction strength." (PMID 40496565, 2025). "In both non-osteoporosis and osteoporosis patients, cell communication analysis revealed that CXCL10-PCC, HSPA1A-OC, and SPARCL-OC are predominantly involved in cell-to-cell contact." (PMID 40496565, 2025).
osteosarcoma (2 papers, 2008 to 2020). A usually aggressive malignant bone-forming mesenchymal neoplasm, predominantly affecting adolescents and young adults. "In addition, miR-233 downregulates the heat shock protein 70 (Hsp70) protein level and downstream JNK/JUN signaling pathways by binding to the HSPA1A 3′UTR, thereby regulating osteosarcoma cells apoptosis." (PMID 33267910, 2020).
viral infection (2 papers, 2020 to 2022). "In the acute phase of viral infection (4 hpi; cluster 2), genes responsive to ER stress, such as HSPA1A, HSPA5, and HERPUD1, were specifically upregulated, suggesting that viral infection affects cellular phenotypes from the early hours after cellular entry." (PMID 33142113, 2020).
adenoma (1 paper, 2021). A neoplasm arising from the epithelium. "Moreover, protein levels of HSPA1A progressively increased from AAH, adenoma, to adenocarcinoma in K mice after 24 weeks of Ade-Cre treatment." (PMID 34858604, 2021).
agranulocytosis (1 paper, 2015). "They found that HSPA1A is a potential off-target of clozapine, which is associated with agranulocytosis." (PMID 25631039, 2015).
alcoholic hepatitis (1 paper, 2022). Acute hepatitis resulting from ingestion of alcohol. "Patients with alcoholic hepatitis exhibit lower gene expression levels of HSPA1A in liver compared with healthy controls." (PMID 35176017, 2022).
allergic rhinitis (1 paper, 2025). Inflammation of the nasal mucous membranes caused by an IgE-mediated response to external allergens. "For example, increased expression levels of HSPA1A mRNA have been observed in COPD lung tissue and mucosal scrapings from patients with allergic rhinitis, which is positively correlated with disease severity and smoking status." (PMID 40553562, 2025).